ZNF316 (zinc finger protein 316)
Description:
May be involved in transcriptional regulation.
Synonyms: MZF-3; ENST00000305834
Tractability: PROTAC: UniProt records ubiquitination sites on it; ubiquitination databases record sites on it; its protein half-life has been measured.
Gene: Protein-coding gene on chromosome 7 (6,637,298 to 6,658,279, forward strand). Ensembl gene ENSG00000205903.
Subcellular location: Nucleus
Gene Ontology:
Molecular function: DNA-binding transcription factor activity, RNA polymerase II-specific; sequence-specific DNA binding
Biological process: regulation of transcription by RNA polymerase II; regulation of DNA-templated transcription
Cellular component: nucleus
Genetic constraint (gnomAD): Loss-of-function variants: 18 observed, 22.72 expected, observed/expected ratio (o/e) 0.79, 90% interval 0.55 to 1.17. The synonymous counts are far from expectation, so gnomAD's model fits this gene poorly and the ratio says little. Missense variants: 1,018 observed, 838.4 expected, observed/expected ratio (o/e) 1.21, 90% interval 1.15 to 1.28. Synonymous variants: 704 observed, 472.57 expected, observed/expected ratio (o/e) 1.49, 90% interval 1.4 to 1.59.
Homologues: Orthologues: chimpanzee ZNF316 (97% identical), macaque ZNF316 (96% identical), dog ZNF316 (86% identical), pig ZNF316 (84% identical), mouse Zfp316 (79% identical), rat Zfp316 (79% identical), guinea pig ZNF316 (77% identical), rabbit ZNF316 (64% identical). Paralogues in human: ZNF787 (15% identical).
Diseases named in the same sentence as ZNF316 in open-access papers:
ZNF316 is named in the same sentence as 1 disease in open-access papers, as found by Europe PMC text mining. Sharing a sentence is not in itself a finding about the gene and the disease. The quoted sentences say what the papers report.
cardiac hypertrophy (1 paper, 2024). "Therefore, the reduced expression of ZNF316 in symptomatic HCM cats may contribute to cardiac hypertrophy and represent a novel therapy target in managing feline HCM." (PMID 38970022, 2024).